GDF15 (growth differentiation factor 15)
Diseases named in the same sentence as GDF15 in open-access papers (continued):
Sharing a sentence is not in itself a finding about the gene and the disease.
cancer (continued). "Taken together, these data suggested that GDF15 promoted cancer stemness conversion by facilitating CD44+ and ALDH1+ cell formation." (PMID 27903972, 2017). "It is conceivable that GDF15 plays a pro-apoptotic protein role in cancer cells, whereas GDF15 acts as an anti-apoptotic protein in non-cancer cells." (PMID 28388574, 2017). "Therapies targeted against GDF15, such as anti-GDF15 antibodies, would be useful for eradication of GDF15high cancer stem-like cells." (PMID 28206960, 2017). "In conditions of acute injury, inflammation, and cancer, GDF-15 will be expressed at a dramatically high level." (PMID 28489602, 2017). "Expression and secretion of GDF15 is heightened in many malignant tissue and cancer cell lines (prostate, colorectal, pancreatic, gastric and oral squamous carcinoma) as compared with their normal tissues or cells." (PMID 29117212, 2017). "In summary, while GDF15 exhibits pleiotropic effects in cancer cells, the majority of studies support a role for GDF15 in disease progression, with overexpression linked to EMT, invasion and metastasis." (PMID 29212236, 2017). "In previous reports, serum levels of GDF15 were enhanced in patients with viral hepatitis, cancer, or metabolic disease compared to healthy controls." (PMID 29222479, 2017). "Consistent with the fact that CSCs are thought to be a minor population of cancer cells, partly due to relatively low proliferating activity, it is possible that GDF15-positive cells represent cancer stem-like cells." (PMID 28206960, 2017). "Patients with advanced-stage cancers, including breast, express high levels of GDF15 in tumor tissues and/or sera." (PMID 29212236, 2017). "Circulating GDF15 levels have been used to predict disease progression in cancer, cardiovascular disease, chronic renal and heart failure, and pulmonary embolism." (PMID 28798540, 2017). "Other studies showed that GDF15 can be a biomarker of poor prognosis in both serum and cancer tissues." (PMID 28206960, 2017). "Except for its direct bioactivity in cancer cells, GDF-15 has frequently been reported to modulate the tumoral microenvironment and regulate the immunization." (PMID 28489602, 2017). "Many previous investigations have revealed a remarkable induction of GDF15 in a number of diseases, such as inflammation, cancer, and various metabolic diseases, suggesting that it is induced as a compensatory measure." (PMID 29222479, 2017). "We found that GDF15 contributes to radioresistance and facilitates cancer stemness conversion through regulation of cellular reactive oxygen species (ROS) via a SMAD-associated pathway." (PMID 27903972, 2017). "Taken together, these studies suggest that GDF15 inhibits cellular ROS generation, which also promotes cancer stemness." (PMID 27903972, 2017). "GDF15 is not only involved in cancer development, progression, angiogenesis and metastasis, but also controls embryonic, osteogenic and hematopoietic development, stress responses, adipose tissue function and cardiovascular diseases." (PMID 28199981, 2017). "In the present study, we found that GDF15 facilitated cancer stemness and radioresistance via activation of Smad1/5, as demonstrated in both cellular and animal studies." (PMID 27903972, 2017). "GDF-15 expression and secretion are both increased in some malignant tissues and cancer cell lines when compared with their normal tissues or cells." (PMID 28489602, 2017). "We then examined another property of cancer stem-like cells, which is the expression of stem-cell markers Oct4, Sox2, and Nanog, after stimulation with GDF15." (PMID 28206960, 2017). "Serum levels of GDF15 were elevated in patients with metastatic colorectal (8/8), prostate (8/9), and breast (6/10) cancers when compared with sera from normal controls." (PMID 29212236, 2017). "We further showed that GDF15 facilitated the conversion of cancer stemness, as assessed by the promotion of CD44+ and ALDH1+ cell populations and spheroid cell formation." (PMID 27903972, 2017).
cancer (continued). "Accumulating evidence suggests that GDF15 is a biomarker for ageing and morbidity of many somatic disorders such as cancer and inflammatory disorders." (PMID 28801589, 2017). "As self-renewal is a typical property of cancer stemness, we assessed this cellular characteristic in GDF15+ cells." (PMID 27903972, 2017). "Taken together, our results demonstrated that GDF15 contributed to radioresistance and cancer stemness by regulating cellular ROS levels via a SMAD-associated signaling pathway." (PMID 27903972, 2017). "Currently, some reports explored the relationship between GDF15 serum levels and some biomarkers in cancers." (PMID 26990020, 2016). "Increasing levels of serum GDF15 have been reported in various cancer patients, such as those with prostate, breast, and colon cancer." (PMID 26892343, 2016). "During cancer development and progression, the role of GDF-15 has remained controversial with different findings depending on the tumor entity and models investigated." (PMID 26741507, 2016). "GDF-15 can promote tumor progression and plays a role in the development of cachexia in late stages of cancer." (PMID 26741507, 2016). "GDF15 plays multiple roles in various pathologies, including inflammation, cancer, cardiovascular disease and obesity." (PMID 26544895, 2016). "Although there is no other literature reporting the familiar results in any other type of cancers, our results indicate that the OSCC patients with missense GDF15 mutations would have a worse prognosis than those with wild-type GDF15." (PMID 26544895, 2016). "GDF15 is widely distributed in mammalian tissues and has multiple functions in various pathologies, including inflammation, cancer, cardiovascular diseases and obesity." (PMID 26497212, 2016). "Despite the growth inhibitory functions of GDF15 and PAI-1, both are negatively correlated with cancer prognosis associated with multiple malignancies." (PMID 26431317, 2015). "Increasing levels of GDF-15 stimulate anti-inflammatory effect on macrophage, antiapoptotic effect on some cancer cells, and antigrowth and antihypertrophic effect at inhibition of remodeling." (PMID 26075263, 2015). "Increased GDF-15 expression is a feature of many cancers including breast, colon, pancreas, and prostate." (PMID 26273671, 2015). "High expression of GDF-15 in tumor is also associated with an increase in serum GDF-15 levels, suggesting the use of serum GDF-15 measurement for the diagnosis and management of cancer." (PMID 26273671, 2015). "Several studies showed that higher expression of GDF-15 mRNA and protein was found in cancer biopsies." (PMID 26273671, 2015). "MIC-1/GDF15 serum levels in cancer are influenced not only by its over-expression, but also depend on how it is processed by the tumor." (PMID 25695521, 2015). "The in vivo cancer related activity of MIC-1/GDF15, has been examined in a number of tumor xenograft studies with mixed results." (PMID 25695521, 2015). "To further advance our understanding of this cytokine in cancer, we have determined how MIC-1/GDF15 deficiency influenced the evolution of PCa." (PMID 25695521, 2015). "GDF-15 is known to be highly expressed in various kinds of malignant tumors; its effect on cell proliferation remains somewhat controversial." (PMID 25033458, 2014). "GDF-15 also plays an important role in tumorigenesis and metastasis since it is dramatically increased in many types of cancers." (PMID 24484525, 2014). "During the follow up in the total population as well as in the non-cancer-population an increasing GDF-15 level was significantly related to subsequent cancer mortality." (PMID 24312445, 2013). "Both inflammatory processes and several cancer diseases can lead to the expression of GDF-15 in several cell types." (PMID 24312445, 2013). "When also including the other available baseline characteristics and biomarkers only GDF-15 was significantly related to cancer morbidity and mortality." (PMID 24312445, 2013).
cancer (continued). "Only GDF-15 independently predicted cancer morbidity and mortality in the context of all biomarkers." (PMID 24312445, 2013). "When comparing the impact of the different biomarkers on outcomes, CRP and GDF-15 were the only biomarkers related to cancer morbidity and mortality." (PMID 24312445, 2013). "There is a dearth of information about the effects of MIC-1/GDF15 in spontaneous models of cancer development, which more closely correspond to cancer biology in man." (PMID 22952779, 2012). "Although there are multiple lines of evidence linking MIC-1/GDF15 to cancer in general and PCa specifically, convincing and consistent data on its biological role in the pathogenesis and progression of cancer is limited." (PMID 22952779, 2012). "The in vivo cancer related activity of MIC-1/GDF15, has also been examined in a limited number of tumor xenograft studies." (PMID 22952779, 2012). "In patients with advanced cancers, serum MIC-1/GDF15 levels rise from an average in non-cancer patients of about 450 pg/ml to up to 10,000–100,000 pg/ml." (PMID 22952779, 2012). "Here we show that that macrophage inhibitory cytokine-1 (MIC-1/GDF15), known to have anorexigenic effects particularly in cancer, provides protection against the development of obesity." (PMID 22514681, 2012). "MIC-1/GDF15 is also expressed by many common cancers, and its serum levels rise approximately in proportion to the stage and extent of disease, providing a potential clinical tool to aid in prevention, diagnosis and prognosis." (PMID 22514681, 2012). "The intensity of GDF15 staining was higher in the primary cancer compared with the lymph node metastases (P=0.035)." (PMID 21468045, 2011). "There have been several reports that GDF15 protein inhibits cell proliferation, similar to TGFβ; conditioned medium collected from GDF15-overexpressing cancer cells suppressed tumor cell growth through the TGFβ signaling pathway." (PMID 21245963, 2011). "Moreover, GDF-15, a cytokine that is abundantly produced by many cancer types, was shown to interfere with T cell activation and anti-PD-1-mediated checkpoint inhibition." (PMID 41596411, 2026). "For example, GDF‐15 has been shown to play a role in cancer development and progression as it was, among other things, found to predict prostate cancer, influence the prognosis of colorectal malignancies and induce cancer‐related cachexia." (PMID 41555670, 2026). "In the clinical field, several investigators have reported that circulating GDF15 levels in patients with cachectic cancer are much higher than those in non-cachectic patients, and this was correlated with cancer-associated weight loss." (PMID 41016991, 2026). "Similarly, we generated the GDF15-mediated signaling pathway map to enhance our understanding of its role and contribute to the existing knowledge in cancer contexts." (PMID 40128491, 2025). "Additionally, local expression of MIC-1/GDF15 in skeletal muscle of cancer patients is significantly increased, promoting appetite suppression and protein breakdown." (PMID 41140691, 2025). "Given its demonstrated anticachectic effects, anti-GDF-15 therapy could substantially address these challenges and improve clinical outcomes in patients with cancer cachexia." (PMID 41294666, 2025). "This may result from that mature NAG-1/GDF15 provokes cancer-surrounding cells like macrophages or endothelial cells to produce cytokines, in turn inducing cancer growth." (PMID 40316530, 2025). "With continued investigation, GDF15 modulation may become a cornerstone of precision medicine, enhancing both survival and quality of life in patients with various types of cancer." (PMID 40868185, 2025). "We hypothesized that these distinct expression patterns of NAG-1/GDF15 forms within cells could lead to the contradictory roles of NAG-1/GDF15 in cancer." (PMID 40316530, 2025).
cancer (continued). "In the cancer environment, tumor cells can secrete the soluble factor GDF15 (Growth and Differentiation Factor 15), which signals to the macrophages and suppress the transforming growth factor β-activated kinase 1 (TAK1)-NF-κB axis for the removal of tumor cells." (PMID 41245273, 2025). "The GDF-15-mediated neural pathway may influence cancer cachexia and negatively affect tumour immunity via SNS activation." (PMID 41294666, 2025). "This review explains the role of growth differentiation factor 15 in cancer, why it matters for patients, and how it may become a new target for treatment." (PMID 41294666, 2025). "Growth differentiation factor 15 (GDF15), a member of the transforming growth factor-beta superfamily, participates in diverse physiological and pathological processes including inflammation and cancer." (PMID 41023695, 2025). "Although GDF15 upregulation is observed in various cancers, its roles, whether pro-tumorigenic or anti-tumorigenic, can differ based on the cancer type and stage." (PMID 40144214, 2025). "GDF15 is a stress-induced cytokine that is normally expressed at low levels, but is highly upregulated in response to tissue damage, inflammation, oxidative stress, and cancer." (PMID 40869331, 2025). "In addition to their potential for treating cancer cachexia, multiple ongoing and planned clinical trials are evaluating GDF-15 and GFRAL inhibitors in combination with ICIs." (PMID 41294666, 2025). "A protein called growth differentiation factor 15 is produced at high levels in many cancers." (PMID 41294666, 2025). "GDF15 protects against tissue injury, acts as a metabolic and immune regulator, and may be a biomarker of obesity, cardiovascular diseases, and various cancers." (PMID 40354065, 2025). "Previous studies have established the close involvement of GDF15 in different cancer stages." (PMID 40144214, 2025). "Despite these limitations, our results suggest that GDF15 could be an important prognostic factor in various types of cancer, with significant clinical implications for cancer treatment and patient care." (PMID 40725563, 2025). "GDF15 suppression has been shown to be beneficial in murine models of cancer cachexia." (PMID 40354065, 2025). "Sixth, serum levels of GDF‐15 are elevated in various types of cancer." (PMID 40700030, 2025). "Furthermore, evidence suggests that GDF-15 plays a role in tumorigenesis and disease progression in cancer patients." (PMID 39967200, 2025). "The accessibility of the GDF-15-mediated signaling pathway will assist researchers in biomedicine to comprehend the functions of various molecules controlled by GDF15 in the progression of cancers." (PMID 40128491, 2025). "Both IL‐6 and GDF‐15 are involved in cancer‐related cachexia, with their elevated levels predicting more severe muscle wasting, reduced physical function and diminished ability to withstand the stresses of surgery and cancer treatment." (PMID 41380167, 2025). "Targeting GDF-15 may help redefine the management of cancer cachexia as a potentially treatable condition, while also enhancing immunotherapy efficacy and expanding therapeutic strategies." (PMID 41294666, 2025). "Therefore, this review provides a comprehensive overview of the emerging role of GDF-15 in cancer pathophysiology, focusing on its involvement in cachexia, immune suppression, and potential as a therapeutic target, supported by promising clinical results." (PMID 41294666, 2025). "Furthermore, serum GDF15 levels as a biomarker are proposed for the early detection and diagnosis of various cancers." (PMID 40128491, 2025). "Given that mRNA translation is closely linked to cancer cell growth, and NAG-1/GDF15 is induced by anticancer compounds affecting various signaling pathways, we focused on investigating whether NAG-1/GDF15 can inhibit growth-related signal transduction." (PMID 40316530, 2025).
cancer (continued). "With the combined upregulation of inflammation, metabolic dysfunction, and muscle wasting in our study, further research should investigate whether GDF15 acts as a link between these upregulated pathways in cachectic cancer patients." (PMID 40558549, 2025). "Additionally, several soluble factors associated with the senescence phenotype were highly expressed in HLA-E positive cancer cells, particularly GDF15, MMP2, and MMP7." (PMID 40959273, 2025). "Independently of food intake, previous preclinical and clinical studies have suggested that GDF15 may contribute to muscle atrophy in cancer cachexia by interacting with the muscle-specific E3 ubiquitin ligases MuRF1 and Atrogin1." (PMID 40558549, 2025). "The high expression of GDF-15 in ULMS may be due to the activation of cancer-related inflammatory processes." (PMID 38818470, 2024). "This study will support the clinical development of ponsegromab as a novel inhibitor of GDF‐15, which may ameliorate key pathologies of cancer cachexia to improve patient symptoms, functionality and quality of life." (PMID 38500292, 2024). "Previous study indicated that GDF15 could suppress apoptosis in cancer cells by in-activating the caspase cascade, which is in line with our data." (PMID 38230211, 2024). "GDF-15 is involved in immune tolerance and is elevated in several acute and chronic stress conditions, often correlating with disease severity and patient prognosis in cancer and metabolic and cardiovascular disorders." (PMID 39394174, 2024). "Moreover, control IgG-treated animal pairs fed with tumor-bearing GDF-15-GFRAL axis-impaired mice showed greater body mass improvement in the tumor group, suggesting a feeding-independent mechanism for GDF-15 in cancer cachexia." (PMID 38254849, 2024). "Preclinical studies in mouse models and non‐human primates implicate GDF‐15 in cancer cachexia." (PMID 38500292, 2024). "Similarly, GFRAL-IR was detected in human normal pancreatic ductal epithelial and cancer cells, which was positively correlated with GDF15 expression." (PMID 38474863, 2024). "The association between elevated GDF-15 levels and adverse clinical outcomes aligns with prior studies identifying GDF-15 as a key mediator of immune evasion and tumor progression across various cancers." (PMID 39766045, 2024). "Among various types of cancers, PCa exhibits the highest GDF15 transcript expression." (PMID 39587633, 2024). "GDF‐15 acts as a global regulator of stress in response to stimuli of varying origin, including environmental, medical therapies (including chemotherapy and radiation therapy) and chronic diseases (e.g., cancer and heart failure)." (PMID 38500292, 2024). "Specifically, GDF-15 seems to limit tumor growth in early tumor stages, whereas cancer cells may exploit GDF-15 to escape immune surveillance in later stages, promoting a protumorigenic environment which supports tumor proliferation and metastatic spread." (PMID 39283723, 2024). "In patients with cancer, while the majority of studies showed that GDF-15 could enhance cancer cell apoptosis, some of them indicated the adverse effects of this factor." (PMID 38409184, 2024). "The use of GDF-15 as a marker for patients who would benefit from such therapy may be a valuable option in such cancers, where anti-PD-1/PD-L1 inhibitors are used as first-line therapy in intermediate- and poor-risk metastatic tumors." (PMID 39000420, 2024). "Importantly, under pathological conditions such as cancer, GDF15 induces other signalling pathways, including CD44, Erb and NF‐kB." (PMID 36992609, 2023). "We searched for specific molecular factors that may help predict whether cancer cells reduce GDF15 expression upon BET inhibition and serve as biomarkers for patient selection." (PMID 37495707, 2023).